CD4 (CD4 molecule)
Diseases named in the same sentence as CD4 in open-access papers (continued):
Sharing a sentence is not in itself a finding about the gene and the disease.
COVID-19 (continued). "We next investigated the relationship between the profile of SARS-CoV-2–specific CD4+ T cells and COVID-19 severity." (PMID 33945513, 2021). "In our previous observations, we found a statistically significant increase in CD4+ or CD8+ naïve T cells in COVID-19 patients with respect to other sample cohorts." (PMID 34944610, 2021). "In summary, recovered COVID-19 individuals presented sustained lower counts of activated CD4+ T cells than healthy controls." (PMID 35069575, 2021). "We detected IFNγ-expressing SARS-CoV-2-reactive CD4+ T cells in only 5% of RTx patients and in 20% of healthy individuals, but in 59% of COVID-19 patients." (PMID 34228322, 2021). "During hospitalization for COVID-19, antiretroviral therapy with lamivudine and tenofovir was administered to 20 patients, except for one patient who refused, whose CD4 T-cell count was 85 cells/μl." (PMID 34646783, 2021). "Here, we report on the immune profile of SARS-CoV-2 CD4 response in hospitalized acute COVID-19 patients stratified by disease severity based on multiple clinical parameters of known relevance in COVID-19 outcome." (PMID 33945513, 2021). "It has been demonstrated that IFN-γ-producing CD4+T cells tended to be lower in severe cases than moderate cases and correlated with disease severity of COVID-19." (PMID 33757410, 2021). "Of note, bendamustine can induce a very delayed T-lymphocyte reconstitution, particularly of CD4+ T cells, raising the possibility that benda alone or benda enhanced by COVID-19 was suppressing this patient’s CD4+ T cells." (PMID 34201591, 2021). "Two months after recovery from COVID-19, patients still presented lower levels of CD4+ T cells, B cells, and granulocytes." (PMID 34578460, 2021). "HIV-1–infected non–COVID-19 controls had a lower median CD4 count (20 cells/mm3, P = 0.03) and higher viral loads (5.37 log mRNA copies/mL, P = 0.0005) owing to proportionally fewer participants being on ART in this group (46.1%)." (PMID 33945513, 2021). "In this regard CD8+ and CD4+ T cells from severe COVID-19 patients are known to have a lower cytotoxic activity and decreased production of IFN-γ respectively, which correlates with age and inflammatory parameters." (PMID 34566957, 2021). "CD4+ T cells from a larger cohort of 34 COVID-19 individuals were stimulated with S protein-pulsed monocytes and proliferating T cells were cloned by limiting dilution." (PMID 34006597, 2021). "In their analysis, the subsets of lymphocytes showed a significant association with inflammatory status in COVID-19, especially CD8+ T cells and CD4+/CD8+ ratio." (PMID 34185801, 2021). "This also indicates the association of these regulatory molecules with the apoptosis of antigen-activated T cells during COVID-19, leading to decreased CD4+ T cell numbers and lowering the percentage of naive T cells." (PMID 34163490, 2021). "Assessing the phenotypical profile of SARS-CoV-2–specific CD4+ T cells, the following trends were observed in less severe forms of COVID-19 (WHO 4 or lower): increased expression of CD38, Ki67, and GrB and reduced expression of HLA-DR." (PMID 33945513, 2021). "A beneficial role of T cells in combating COVID-19 would be in line with observations that CD4+ and CD8+ T cells are protective against the closely related SARS-CoVs." (PMID 34878838, 2021). "At the same time, through autopsy of COVID-19 infected patients, extensive infiltration of neutrophils, macrophages and CD4 + T lymphocytes were found in their cardiomyocytes." (PMID 34074305, 2021). "In COVID-19, the CD4 response was characterized by limited expression of IFN-γ and was enriched in cells coexpressing IL-2 and TNF-α." (PMID 33945513, 2021). "CD4+ T cell and antibody responses were observed in all COVID-19 patients analyzed, and CD8+ T cell responses in most." (PMID 33530624, 2021). "Of the patients recovered from COVID-19, 100% had S protein-specific CD4+ T cells and 70% had S protein-specific CD8+ T cells in blood samples." (PMID 33810287, 2021).
COVID-19 (continued). "A decrease of CD4+ T and CD8+ T cells was found in the context of COVID-19, and lymphopenia has been implicated as a risk factor for ARDS and mortality, suggesting that the adaptive immune system in the severe infection subgroup was less activated." (PMID 34439967, 2021). "Lymphopenia is a common feature of severe COVID-19, characterized by drastically reduced absolute numbers of CD4+ and particularly CD8+ T cells which correlates with COVID-19 severity and associated mortality." (PMID 33859644, 2021). "Severe COVID-19 is characterized by reduced numbers of CD4+ and CD8+ T-cells, and peripheral lymphopenia is often associated with functionally exhausted T-cells, having decreased proliferative ability and elevated levels of pro-inflammatory cytokines." (PMID 34830421, 2021). "In a retrospective study in 522 COVID-19 patients, a sharper reduction of T cells (including total T cells, CD4+ and CD8+ T cells) occurred in patients requiring intensive care unit (ICU) care vs. non-ICU patients." (PMID 34766001, 2021). "Reduced levels of CD4+T and CD8+T cell were not only associated with the severity of COVID-19, but also with poor outcomes." (PMID 33435865, 2021). "Only the in vitro expansion capacity of memory CD4+ from asymptomatic COVID-19 patients was significantly lower." (PMID 33741972, 2021). "The frequency of Th17 cells (CD4+IL-17+) was reduced in both mild and severe COVID-19 group, whereas the frequency of Th2 cells (CD4+ IL-4+) was higher in both COVID-19 groups, compared to healthy donors." (PMID 33692788, 2021). "In relation to the primary endpoint of the study, influenza and COVID-19 vaccines induced an increase in CD4+T cells." (PMID 34959898, 2021). "Analysis of the COVID-19 CD4+ T cell hotspot phenotypes using root mean square deviation (RMSD) analysis identified three phenotypic groups." (PMID 34350827, 2021). "Compared to hospitalized COVID-19 patients during acute disease, patients at 3–6 months of convalescence showed higher proportions of CD4+ and CD8+ CCR7–CD45RA+ effector T cells and reduced expression of the proliferation marker Ki-67." (PMID 34595175, 2021). "We did not observe significant difference between the BMI groups of biomarkers previously reported as reflects of COVID-19 inflammatory immune response such as neutrophils to lymphocytes or CD4 to CD8 ratios." (PMID 34038475, 2021). "This complements the known anti-viral properties of IFNγ and the enrichment of these IFNγ-secreting CD4+ TEM cells during COVID-19 convalescence strongly suggests their role in mediating effective and long-lasting viral clearance." (PMID 34113347, 2021). "Demographic and laboratory findings of children with COVID-19 according to different CD4+/CD8+ T cells ratio." (PMID 33937149, 2021). "Nevertheless, in comparing patients with COVID-19 with patients with bacterial pneumonia, we observed that CD4+ T cells and, in particular, TRM17 cells were more clonally expanded in the BALF of the virally infected group." (PMID 33622974, 2021). "Patients with mild-to-moderate COVID-19 have activated CD4+ and CD8+ T cells, increased antibody-producing cells and follicular helper T cells, as well as IgM and IgG antibodies in blood prior to symptomatic recovery." (PMID 33525459, 2021). "Some of the included studies explored the levels of LYM subsets in patients with different clinical stages of COVID-19, of which the largest number was CD4+ T cells." (PMID 33557779, 2021). "Like in the case of CD4+ T cells, a significant number of B cells is found in long-term after recovery from mild COVID-19, targeted towards the Spike protein of SARS-CoV-2." (PMID 33777028, 2021). "Proliferating cytotoxic CD8+ T cells and CD4+ follicular helper T cells (Tfh) were common in COVID-19 patients with reduced proportions of regulatory T cells (Treg)." (PMID 34527720, 2021).
COVID-19 (continued). "Several studies suggested a potential role of circulating CD4+ T cells in COVID-19 severe respiratory syndrome and multi-organ systemic inflammation." (PMID 34335703, 2021). "The use of predicted SARS-CoV-2 class I epitopes of optimal size can also underestimate the level of virus-specific CD8+ T cells in COVID-19 convalescents due to the limitations in epitope-predicting algorithms, especially for CD4+ T cells." (PMID 34452355, 2021). "Another study suggested that decreased perforin and granzyme A levels in CD4+ T cells, CD8+ T cell and NK cells is associated with severely afflicted COVID-19 patients." (PMID 34075347, 2021). "Studies have shown that lymphocytes in patients with COVID-19 show a significant decreasing trend, among which CD4+ and CD8+T lymphocytes are the most obvious." (PMID 34490135, 2021). "Using HLA class I and II predicted peptide “megapools,” circulating SARS-CoV-2-specific CD8+ and CD4+ T cells were identified in COVID-19 acute, mild and convalescent patients." (PMID 34910301, 2021). "Together, these results indicated a potential role of TREM-2 in the CD4+ T cell responses in patients with COVID-19." (PMID 34878838, 2021). "As the results shown, miR-30b-5p was negatively correlated with CD4 + T cell counts (r = − 0.41, P = 0.027) and marginally positively correlated with fasting plasma glucose in COVID-19 patients (r = 0.37, P = 0.052)." (PMID 34876159, 2021). "Different studies have shown that in patients with severe COVID-19, total lymphocytes and particularly CD4+, CD8+ T cells and B cells were significantly lower than those in patients with the mild form." (PMID 33669527, 2021). "In the COVID-19(+) patients we noticed the lowest median proportion of CD25+ CD4+, and CD8+ CD25+ cells compared to the HC group and COVID-19(−) virus group (respectively for CD4+ CD25+: 3.0 vs. 19.8 vs. 24.1, for CD8+ CD25+: 0.2 vs. 2.5 vs. 3.4, p < 0.05)." (PMID 33419040, 2021). "Comparing the immune function of the deceased patients with the recovered patients with COVID-19, we found that CD4 + T cells, CD8 + T cells, B cells and NK cells deceased more severely in the deceased patients." (PMID 33711813, 2021). "Since COVID-19 patients are immunosuppressed, the adaptive form of immunity (lymphocytopenia in lymphocytes T CD4+ and CD8+) is remarkably declined, thus having a defective immune response." (PMID 34575758, 2021). "Along these lines, reduced numbers of CD4+ Tregs have been observed in severe cases of COVID-19 together with increased levels of cytotoxic follicular helper cells and cytotoxic T helper cells." (PMID 34267671, 2021). "Final products from COVID-19 recovered individuals showed higher central memory CD4+ and CD8+ T cell levels, compared to unexposed individuals; however, the differences were not significant." (PMID 35003063, 2021). "Although HCoV-responsive T cells are ubiquitous, their frequencies and the frequencies of SARS-CoV-2–cross-reactive CD4+ T cells decreased with age, consistent with an increased vulnerability of the elderly to severe COVID-19 disease." (PMID 34465633, 2021). "We found a stronger and broader SARS-CoV-2 S protein-specific CD4+ T cell response in most COVID-19 convalescent patients." (PMID 34805136, 2021). "Significant elevation and unusual phenotypes of CD4+ cells, which exhibit both a proliferative exhausted phenotype and a clonally expanded cytotoxic phenotype, were also observed in mild and moderate COVID-19 cases." (PMID 35011632, 2021). "Our observation of the decline of CD38+ CD4+ cell population in COVID-19(+) patients relative to other infections was shown here for the first time." (PMID 33419040, 2021). "In our previous study we observed a significant lower median absolute count of CD4+ cells in patients with COVID-19(+) compared to healthy control while the CD4+ cell had mainly memory profile not effector profile." (PMID 33419040, 2021).
COVID-19 (continued). "A case was described in a newly diagnosed HIV patient with COVID-19 who presented a severe depletion of CD4 T cells, fine reticular changes in CT scan, and an elevated level of lactate dehydrogenase (LDH), successfully treated with TMP-SMX." (PMID 34436124, 2021). "In patients with severe disease, COVID-19 produces an immunosuppressive state that is described by a quantitative decrease in T lymphocytes, particularly those of CD4+ T cells, CD8+ T cells, and natural killer cells." (PMID 34579250, 2021). "Cumulative data indicated that COVID-19 significantly influenced the distribution of blood CD4 T cell lineages." (PMID 34373466, 2021). "We found that MHC-II blockade significantly reduced exosome-dependent T-cell activation, confirming that an antigen-presenting activity of MILD COVID-19 patient exosomes was the actual driving force of CD4+ T-cell activation." (PMID 35111156, 2021). "Previous studies have shown broad T cell responses in a majority of subjects recovering from COVID-19, in particular a high frequency of CD4+ T cells specific to the spike protein." (PMID 34627082, 2021). "The CD8 + and CD4 + T inflammatory cells, which play a vital role in the clearance of viruses, were detected in 70% and 100% of the COVID-19 patients, respectively." (PMID 33519271, 2021). "Both M protein and anti-CD3 Ab induced CD3ζ (Tyr83), ZAP70 (Tyr319), and STAT1 (Ser727) phosphorylation in COVID-19 CD4+ T cells." (PMID 34878838, 2021). "Results showed that the frequency of effector-memory and TEMRA CD4 T cells expressing perforin from a subset of COVID-19 patients was higher than in HC." (PMID 33777054, 2021). "Surprisingly, a higher than normal naive-to-memory CD4+ T cell ratio has been observed suggesting an impact on the differentiation of naive to memory T cells in COVID-19 patients." (PMID 35965490, 2021). "A clinical trial demonstrated that Tα1 restored CD8+ and CD4+ T cell numbers in severe COVID-19 patients with lymphopenia and reversed the PD-1 and Tim-3 expression on exhausted/senescent CD8+ T cells." (PMID 33808998, 2021). "Diverse subpopulations of T lymphocytes such as CD8+T, CD4+T central memory, Mucosal-associated invariant T (MAIT), natural killer (NK), and γδ T cells were reduced, while B plasmablasts were expanded in COVID-19 cancer patients." (PMID 34716309, 2021). "Although IFN-γ appears to be the dominant cytokine produced by CD4+ T cells in COVID-19 patients, some studies reported IFN-γ to be unaltered or even decreased reflecting reduced functional T cell diversity." (PMID 34867933, 2021). "No significant change occurred in lymphopenia B cells and CD8 + Tlenfocyte counts for severe COVID-19 patients, while a decrease in CD4 + T lymphocyte counts was noted." (PMID 33641314, 2021). "Cellular immune responses consisting of CD3+ T, CD4+ T, and CD8+ T cells response underlying immunopathogenesis in COVID-19, which are critical for the control of coronavirus infection." (PMID 35127733, 2021). "Next, we analyzed the percentage of some subsets of CD4+ T lymphocytes in the asymptomatic and symptomatic COVID-19 individuals." (PMID 34578138, 2021). "This population has a higher prevalence of HIV than other populations of pregnant women in which COVID-19 has been investigated, have taken cART as the standard of care with good adherence, had suppressed viral load and high CD4 cell counts." (PMID 34208954, 2021). "Analyses of blood cells from COVID-19 patients also showed significantly increased levels of exhaustion markers in CD4+ and CD8+ T cells." (PMID 35128530, 2021). "Both, post COVID-19 Ab− and Ab+, had significantly higher cytokine tp CD4+ NCAP reactive T cells compared to HC (Ab−: p = 0.04; Ab+: p = 0.008)." (PMID 34322120, 2021). "Our results also revealed that COVID-19 patients displayed reduced frequency of Mycobacterium tuberculosis–specific CD4+ T cells, with possible implications for TB disease progression." (PMID 33945513, 2021).
COVID-19 (continued). "Lymphopenia is a common feature of SARS-CoV-2 infection in severe COVID-19 patients, including a drastic reduction in T-cells (CD4+ and CD8+) and CD19+B cells." (PMID 33757410, 2021). "The frequency of SARS-CoV-2-specific CD4+ T cells or CCR6− peripheral Tfh cells in COVID-19 patients has been shown to correlate with virus-neutralizing antibody levels." (PMID 34502427, 2021). "A recent cross-sectional study of COVID-19 recovered individuals analyzed >6 months after infection has calculated t1/2 of ∼3.5 months for CD4 and CD8 T cells detected with activation induced markers." (PMID 38626271, 2021). "A detectable SARS-CoV-2-specific CD4+ T cell response was found in 57.1% and 47.4% of KTRs 4 and 6 months after COVID-19, respectively." (PMID 34578460, 2021). "Another phenotype of CD4+ T cells was consistently observed in those COVID-19 patients where T-REX revealed a hotspot." (PMID 34350827, 2021). "We found that patients with critical COVID-19 had decreased lymphocyte values including: T lymphocytes, CD4+ cells, B lymphocytes and NK cells." (PMID 34064802, 2021). "After SARS-CoV-2 infection, the only alteration on the memory T cells was on the frequency of central memory CD4+ T cells, also higher in the COVID-19 as compared to the unexposed group." (PMID 34571855, 2021). "A robust memory CD4+ T cell proliferation in the pre-COVID-19 sample was detected against NL63 and 229E S proteins, whereas the response to HKU1 and OC43 was limited and the response to SARS-CoV and SARS-CoV-2 undetectable." (PMID 34006597, 2021). "Overall, neutrophils (CD16+/−) dominated in the respiratory samples of COVID-19 patients, with varying levels of monocytes/macrophages, T-cells (CD4+ and CD8+), NK cells, and B cells." (PMID 34462740, 2021). "COVID-19-related impairments in CD4+ T cells promoted the excessive activation and possible subsequent exhaustion of CD8+ T cells." (PMID 34578460, 2021). "In moderate COVID-19 cases, bronchoalveolar macrophage-epithelial interactions promote an increase in IL-6 and a decrease in the counts of total T-cells, particularly CD4+ and CD8+ T-cells." (PMID 32517353, 2020). "Then, the following equation was derived: Probability (severe COVID-19) = 1/1 + exp − [− 0.483 + (− 0.005 × CD4+ T cell count) + (0.111 × NLR) + (0.003 × D-dimer)]." (PMID 32985562, 2020). "Intriguingly, correlations were seen between low frequencies of naive CD8+ and CD4+ T cells, age, and COVID-19 disease severity." (PMID 33010815, 2020). "The results show that the lymphocytopenia in patients with COVID-19 was mainly manifested by decreases in the CD4+ T lymphocyte number and the CD4+/CD8+ ratio." (PMID 32976531, 2020). "SARS-CoV-2 S-reactive CD4+ T cells were found in 83% of COVID-19 patients, which targeted both C and N terminal epitopes and expressed markers of recent activation (CD38 and HLA-DR)." (PMID 33362759, 2020). "While in the advanced stage of COVID-19, the CD4 cells exhibit functional exhaustion and the absolute number of them decreased significantly, and the expression of ACE2 decreased as well." (PMID 33195212, 2020). "In the patients with COVID-19, the decreased number of CD4+ T lymphocytes was positively correlated with the decreased number of total lymphocytes." (PMID 32976531, 2020). "Clinical investigations of severe COVID-19 patients consistently report neutrophilia and lymphopenia, with significantly depressed CD4+ T cell counts and decreased IFN-γ expression, as well as reduced numbers of regulatory and memory T cells." (PMID 32695122, 2020). "In the patients with COVID-19, the total number of peripheral blood lymphocytes decreased mainly as the number of CD4+ T lymphocytes decreased." (PMID 32976531, 2020). "Our data further revealed concomitant response of three major clusters of memory T cells (CD8+ TEM, CD8+ TTE, and CD4+ TTE) in the adaptive immune system of the COVID-19 patients." (PMID 32796814, 2020).